CYB5R4 (cytochrome b5 reductase 4)
Description:
NADH-cytochrome b5 reductase involved in endoplasmic reticulum stress response pathway. Plays a critical role in protecting pancreatic beta-cells against oxidant stress, possibly by protecting the cell from excess buildup of reactive oxygen species (ROS). Reduces a variety of substrates in vitro, such as cytochrome c, feericyanide and methemoglobin.
Synonyms: b5+b5R; NCB5OR; dJ676J13.1; cb5/cb5R
Tractability: Small molecule: a structure with a bound ligand is known. PROTAC: ubiquitination databases record sites on it; its protein half-life has been measured.
Gene: Protein-coding gene on chromosome 6 (83,859,646 to 83,967,423, forward strand). Ensembl gene ENSG00000065615.
Subcellular location: Endoplasmic reticulum
Pathways (Reactome):
Transport of small molecules: Erythrocytes take up carbon dioxide and release oxygen
Gene Ontology:
Molecular function: cytochrome-b5 reductase activity, acting on NAD(P)H; NAD(P)H oxidase H2O2-forming activity; oxidoreductase activity, acting on NAD(P)H, heme protein as acceptor; heme binding; cytochrome-b5 reductase activity, acting on NADH; oxidoreductase activity
Biological process: reactive oxygen species metabolic process; superoxide metabolic process; bicarbonate transport; cell development; detection of oxygen; glucose homeostasis; insulin secretion; response to antibiotic
Cellular component: endoplasmic reticulum; perinuclear region of cytoplasm; endoplasmic reticulum membrane
Genetic constraint (gnomAD): Loss-of-function variants: 25 observed, 42.87 expected, observed/expected ratio (o/e) 0.58, 90% interval 0.42 to 0.81. The upper end of that interval is the gene's LOEUF score, 0.81, which puts it in group 3 of 6, group 1 being the genes least tolerant of losing a copy. Missense variants: 373 observed, 419.17 expected, observed/expected ratio (o/e) 0.89, 90% interval 0.82 to 0.97. Synonymous variants: 132 observed, 142.15 expected, observed/expected ratio (o/e) 0.93, 90% interval 0.81 to 1.07.
Homologues: Orthologues: chimpanzee CYB5R4 (100% identical), macaque CYB5R4 (96% identical), rabbit CYB5R4 (89% identical), pig CYB5R4 (88% identical), dog CYB5R4 (86% identical), guinea pig CYB5R4 (85% identical), rat Cyb5r4 (83% identical), mouse Cyb5r4 (81% identical), tropical clawed frog cyb5r4 (57% identical), zebrafish cyb5r4 (52% identical), Drosophila melanogaster CG11257 (33% identical), Caenorhabditis elegans Y52B11A.3 (32% identical). Paralogues in human: CYB5R1 (18% identical), CYB5R3 (16% identical), CYB5RL (16% identical), CYB5R2 (15% identical), OXNAD1 (12% identical).
Diseases named in the same sentence as CYB5R4 in open-access papers:
CYB5R4 is named in the same sentence as 12 diseases in open-access papers, as found by Europe PMC text mining. Sharing a sentence is not in itself a finding about the gene and the disease. The quoted sentences say what the papers report.
diabetes (2 papers, 2017 to 2022). "Several studies have suggested that the loss of CYB5R4 results in diabetes mellitus as evidenced by mitochondrial dysfunction, disrupted ion channel signaling and iron homeostasis, and the progressive loss of white adipose tissue in the liver." (PMID 36441026, 2022). "Two of our network genes, NNT (associated with diabetes in mice) and CYB5R4, are both involved in NADPH metabolism." (PMID 29073909, 2017). "These are novel findings and suggest that CYB5R4 may be a unique therapeutic target for those suffering with diabetes mellitus." (PMID 36441026, 2022). "Therefore, interrogating the mechanisms involved in CYB5R4-mediated pancreatic beta cell protection must be performed to facilitate the development of high-quality therapies for diabetes mellitus." (PMID 36441026, 2022). "Studies aimed at elucidating the mechanisms by which CYB5R4 might be mediating the pathogenesis of diabetes, and the assessment of potential interacting partners in vitro and in vivo would further facilitate the development of new therapeutic avenues." (PMID 36441026, 2022). "These unique findings identify a unique enzyme in CYB5R4 that could be targeted therapeutically for those suffering from diabetes mellitus." (PMID 36441026, 2022). "Notably, knockout of CYB5R4 caused early-onset diabetes in mice, irrespective of peripheral insulin sensitivity." (PMID 36441026, 2022).
osteoporosis (1 paper, 2025). A condition of reduced bone mass, with decreased cortical thickness and a decrease in the number and size of the trabeculae of cancellous bone (but normal chemical composition), resulting in increased fracture incidence. "The results indicate that the expression level of the CYB5R4 gene has a notably higher influence on the osteoporosis diagnostic model compared to other factors, while the expression level of the CES2 gene has a lower impact on the osteoporosis diagnostic model relative to other factors." (PMID 40918403, 2025). "Our findings suggest that CYB5R4 may contribute to osteoporosis pathogenesis by modulating lipid metabolism and oxidative stress in bone cells." (PMID 40918403, 2025).
psoriasis (1 paper, 2024). An autoimmune condition characterized by red, well-delineated plaques with silvery scales that are usually on the extensor surfaces and scalp. "Then, the expression of top 5 potential candidate genes (PBX1, CYB5R4, SAR1A, CXCR5, MFSD6) of miR-3074-5p was detected in normal and psoriasis tissues by qPCR; our result revealed that PBX1 was the most upregulated genes in psoriasis tissues compare to normal ones." (PMID 38240925, 2024).
type 2 diabetes (1 paper, 2014). "Based on an analysis of the evolutionary history of candidate genes, we showed that common 5′ variants in CDKAL1, CYB5R4, GAD2, and PPARG as well as an intronic type 2 diabetes-associated CDKAL1 variant exhibit non-neutral evolutionary patterns." (PMID 25222615, 2014).
neurodevelopmental disorder (1 paper, 2021). A behavioral and cognitive disorder with onset during the developmental period that involves impaired or aberrant development of intellectual, motor, or social functions. "A mutation in CYB5R4 that leads to a truncated version of Ncb5or has been implicated in neurodevelopmental disorders, but a potential mechanistic defect is unknown." (PMID 34957217, 2021).
CYB5R4 also shares sentences with these, for which no sentence is quoted: cardiovascular diseases (1 paper); Cranial meningocele (1); diabetic kidney disease (1); Insulin resistance (1); partial epilepsy (1); Sepsis (1); trigonocephaly (1).